RELA (RELA proto-oncogene, NF-kB subunit)
Diseases named in the same sentence as RELA in open-access papers (continued):
Sharing a sentence is not in itself a finding about the gene and the disease.
endometrial tumor (1 paper, 2022). "A molecular profiling study of CD44 and ALDH expressing endometrial tumor circulating cells found increased expression of NF-κB member RelA associated with tumor infiltration and EMT." (PMID 35328833, 2022).
endometrioid adenocarcinoma (1 paper, 2016). An adenocarcinoma characterized by the presence of malignant glandular epithelial cells resembling endometrial cells. "We found that NF-κB RelB protein, but not RelA, displayed high expression in EC samples and cell lines, with predominant elevation in endometrioid adenocarcinoma (EEC)." (PMID 27711077, 2016).
endometritis (1 paper, 2022). An acute or chronic, usually bacterial infectious process affecting the endometrium. "Thus, this study aimed to determine gene transcription of NF‐κB subunits (RelA; NF‐κB1; NF‐κB2), proinflammatory molecules (MCP‐1; IL‐6) and hyaluronan synthases (HAS 1; HAS 2; HAS 3) in endometritis and compare them with the intensity and type of inflammatory cell infiltration." (PMID 35182075, 2022).
gallbladder carcinoma (1 paper, 2024). "In gallbladder carcinoma, knockdown of ANXA4 resulted in decreased transcription activity of RELA and lower expression of NF-κB target genes; moreover, inhibition of NF-κB was associated with suppressed ANXA4 expression." (PMID 38417630, 2024).
Genital ulcers (1 paper, 2026). "Herein, we report a pediatric patient who presented with recurrent, severe oral and genital ulcers from the age of five years and was diagnosed with RAID following a documented RelA gene mutation." (PMID 41591550, 2026).
glaucoma (1 paper, 2024). Increased pressure in the eyeball due to obstruction of the outflow of aqueous humor. "Unlike RelA, RelB remained understudied in glaucoma research." (PMID 38824526, 2024).
glycogen storage disease (1 paper, 2022). "For example, HCA developed in a mouse model of glycogen storage disease and liver tumors similar to inflammatory HCA developed in NF-κB/RelA double knockout mice." (PMID 36233225, 2022).
gynecological cancers (1 paper, 2025).
HCMV infection (1 paper, 2022). "This study on acute HCMV infection showed that the p-Ser536 RelA/p65 negatively affects IE protein levels and NF-κB activity by binding to MIEP." (PMID 35269913, 2022). "Therefore, we explored the effects of changes in hsa-miRs during HCMV infection on the phosphorylation of RelA/p65 (Ser536) to understand how cellular miRNAs are involved in modulating host signaling after HCMV entry." (PMID 35269913, 2022).
HELLP syndrome (1 paper, 2021). A life-threatening condition that can potentially complicate pregnancy. "For the early diagnosis of HELLP syndrome, some studies suggest using novel genetic biomarkers in association with laboratory markers, new potential tools with clinical utility (Galectin-1 and p65/RelA immunoexpression of placental NF-kB)." (PMID 34828527, 2021).
hepatoblastoma (1 paper, 2024). Hepatoblastoma (HB) is a malignant hepatic tumor and is the most common pediatric liver cancer. "STAT3 and RELA/p65 formed a complex in HepG2 hepatoblastoma cells stimulated with IL-1 and IL-6, and NF-κB RELA/p65 homodimers were shown to cooperate with STAT3 in Hep3B cells in response to IL-1." (PMID 39641161, 2024).
Hirschsprung disease (1 paper, 2024). Hirschsprung disease (HSCR) is a congenital intestinal motility disorder that is characterized by signs of intestinal obstruction due to the presence of an aganglionic segment of variable extent in the terminal part of the colon. "Therefore, in this study, we have analyzed the expression of the main subunits of the NF-κB pathway, RELA and NF-KB1, together with other NF-κB-related and pro-inflammatory factors, on HSCR patient’s samples with the aim of analyzing their potential role in Hirschsprung’s disease." (PMID 39199380, 2024).
inflammatory skin disease (1 paper, 2024). Inflammatory skin disorders covers a broad category that includes many conditions ranging in severity, from mild itching to grave medical health complications These disorders are common in people of all ages and races. "The inhibition of nuclear translocation of the two SRTFs, NF‐κB RelA and pSTAT3, in human KCs underlied the silencing of the key genes mediating AD and other inflammatory skin diseases." (PMID 38846687, 2024).
injury (1 paper, 2019). Damage inflicted on the body as the direct or indirect result of an external force, with or without disruption of structural continuity. "Additionally, it also can regulate the expression of numerous genes that play a key role in the inflammatory response during human and experimental kidney injury; most of these genes are regulated by RELA/P50." (PMID 31281825, 2019).
insomnia (1 paper, 2024). A sleep disorder characterized by difficulty in falling asleep and/or remaining asleep. "A transcription factor (TF)–target analysis of the TRRUST database reveals that numerous targets are regulated by TFs such as NFKB1, RELA, SP1, JUN, and others, suggesting that these TFs may play an important role in insomnia." (PMID 38927034, 2024).
Intervertebral disk degeneration (1 paper, 2017). The presence of degenerative changes of intervertebral disk. "We also demonstrated that genetic reduction in the level of the NF‐κB subunit p65(RelA) in the Ercc1−/∆ progeroid mouse model of accelerated aging delayed the onset of age‐related pathology including muscle wasting, osteoporosis, and intervertebral disk degeneration." (PMID 28229533, 2017).
Jaundice (1 paper, 2018). Yellow pigmentation of the skin due to bilirubin, which in turn is the result of increased bilirubin concentration in the bloodstream. "It is speculated that the YCSND can treat jaundice by inhibiting the expression of c-jun, RELA, EGF, and EGFR." (PMID 30671125, 2018).
Kaposi's sarcoma (1 paper, 2020). A malignant neoplasm characterized by a vascular proliferation which usually contains blunt endothelial cells. "Recently, Wang et al59 certified that IKBKE promotes NF‐κB subunit RelA (also known as p65) phosphorylation at serine 468, which correlated with NF‐κB activation and inflammatory cytokine expression in Kaposi sarcoma." (PMID 31733040, 2020).
keloid (1 paper, 2022). An irregularly shaped, elevated mark on the skin caused by deposits of excessive amounts of collagen during wound healing. "In contrast, in diseased keloids, RELA was mainly expressed in Endo0, showing a distinct apoptotic profile, and its signal intensity was significantly lower than that of Endo2." (PMID 36082167, 2022). "We next performed immunohistochemical staining for RELA on pathological sections of four keloids." (PMID 36082167, 2022).
kidney cancer (1 paper, 2023). Primary or metastatic malignant neoplasm involving the kidney. "Interestingly, among the top co-upregulated TFs in kidney cancer, we prioritized the MYC proto-oncogene, CCAAT Enhancer Binding Protein Data (CEBPD) and RELA proto-oncogene, NK-kB subunit (RELA)." (PMID 37047552, 2023).
lentivirus infection (1 paper, 2011). Virus diseases caused by the Lentivirus genus. "To test whether IκBα degradation is necessary for γHV68-induced RelA degradation, we established Mavs+/+ MEFs stably expressing the IκBα super-suppressor, IκBαΔN, by lentivirus infection and confirmed IκBαΔN expression by immunoblot." (PMID 22110409, 2011). "When exogenous MAVS and IKKβ were re-introduced by lentivirus infection, γHV68 infection induced a transient RelA degradation, bolstering the specific requirement for MAVS and IKKβ in RelA degradation triggered by γHV68 infection." (PMID 22110409, 2011).
leukocytosis (1 paper, 2025). "Haploinsufficiency of p65, encoded by RELA, can present in patients with early onset mucosal ulcers, recurrent fevers, and leukocytosis." (PMID 40842819, 2025).
lipid metabolism disorders (1 paper, 2025). "This study explored the relationship between impaired RelA signaling and lipid metabolism disorders in hepatocytes, and how they synergistically contribute to the advancement of MASLD." (PMID 39910053, 2025). "Lipid accumulation suppresses RelA signaling, remodeling the ER stress response and exacerbating lipid metabolism disorder, ultimately leading to hepatocyte apoptosis and necroptosis." (PMID 39910053, 2025). "However, when excessive lipid accumulation occurs within hepatocytes, this mutual promotion may be inhibited, leading to impairment of the RelA signaling and consequently exacerbating lipid metabolic disorders." (PMID 39910053, 2025).
Listeria infection (1 paper, 2010). "Although RelA/p65-mediated Cxcl-2 production exhibited a slower kinetic as compared to following Listeria infection, a significant number of Cxcl-2+ cells was detected." (PMID 21124989, 2010).
liver cirrhosis (1 paper, 2025). "1.SP1, RELA, and NFKB1 were identified as key regulators in regulating the liver cirrhosis process." (PMID 41586310, 2025).
metabolic dysfunction-associated steatotic liver disease (1 paper, 2025). Metabolic dysfunction-associated steatotic liver disease (MASLD, formerly known as nonalcoholic fatty liver disease or NAFLD) is a type of liver disease that is not caused by alcohol. "However, the specific role of RelA in hepatocytes during the progression of metabolic dysfunction-associated steatotic liver disease (MASLD) is not well understood." (PMID 39910053, 2025).
metastatic melanoma (1 paper, 2016). A melanoma that has spread from its primary site to another anatomic site. "We focused on RelA, due to its negative association with miR-7-5p expression and emerging evidence establishing it as a potential target for metastatic melanoma treatment." (PMID 27203220, 2016).
mononucleosis (1 paper, 2014). "Murid herpesvirus-4 (MuHV-4), which causes mononucleosis in infected mice, expresses its ORF73 protein to target the NFκB family member RelA/p65 for proteasomal degradation." (PMID 25314029, 2014).
muscle atrophy (1 paper, 2023). The loss of muscle tissue due to inactivity or disease. "Our molecular docking results showed that Aloin A had good binding interactions with HSP90AA1, AKT1, CTNNB1, BCL2L1, RELA, TNF, AKT3, the ranging from −7.9 to −8.9 kcal/mol, suggesting that Aloin A stably combined with these proteins for attenuating cancer related muscle atrophy." (PMID 38180061, 2023).
neutropenia (1 paper, 2025). A decrease in the number of neutrophils found in the blood. "SPINK5, RELA and CARD11 were retrieved and seem to be consistent with the clinical picture characterized by neutropenia associated to immune dysregulation." (PMID 40725177, 2025). "When the panel of IEI is studied with a high sensitivity, some interesting data are found, at least for RELA and CARD11, showing more consistent connection with the neutropenia feature." (PMID 40725177, 2025).
opioid dependence (1 paper, 2023). "RELA protein plays a significant role in the downstream activation of the OPRD1 (also known as DOR, δ-opioid receptor, or delta-opioid receptor) is a paralog of OPRM1 associated with opioid dependence gene that encodes the delta-opioid receptor (DOR) protein in humans." (PMID 37434949, 2023).
Oral ulcer (1 paper, 2026). Erosion of the mucous mebrane of the mouth with local excavation of the surface, resulting from the sloughing of inflammatory necrotic tissue. "Oral ulcers (including aphthous lesions) occurred in 88% of patients and were particularly prominent in monogenic NF-κB–related disorders (A20, NEMO, RELA)." (PMID 41562716, 2026).
osteosclerosis (1 paper, 2022). Abnormally high bone density. "Mutation in the RELA gene has been found responsible for human neonatal osteosclerosis." (PMID 36011257, 2022).
ovarian endometriosis (1 paper, 2023). A non-neoplastic disorder characterized by the growth of endometrial tissue in the ovaries. "In the case of recurrence of ovarian endometriosis, both inverse and direct relations between RelA (p65) and PR were reported; however, both researchers considered PR isoform B as predominant." (PMID 36769226, 2023).
ovarian serous cystadenocarcinoma (1 paper, 2020). A malignant serous cystic epithelial neoplasm arising from the ovary. "Pearson correlation analysis showed that EGFR (R = 0.16, P = 0.00072), PTEN (R = 0.098, P = 0.043), SIRT1 (R = 0.094, P = 0.013), RELA (R = 0.18, P = 0.00013) and CREB1 (R = 0.16, P = 0.00094) were significantly correlated with LDHAP5 expression in ovarian serous cystadenocarcinoma." (PMID 32536817, 2020).
Pca (1 paper, 2024). "Previous studies have shown that RELA plays a key role in the initial stages of Pca, and this study found that RELA has an important role in the carcinogenesis, development and metastasis of PCa." (PMID 38835789, 2024). "Next, cellular experiments were performed to verify the role of RELA in proliferation and migration in PCa cells, meanwhile, based on immunohistochemistry, we verified the difference of RELA expression between PCa primary foci and bone metastasis." (PMID 38835789, 2024). "The results of several analyses indicate that RELA plays a crucial role in the ontogenesis, progression, and metastasis of PCa." (PMID 38835789, 2024). "Therefore, RELA is likely to be a new therapeutic target for advanced PCa, and its complex biomolecular function is worthy of subsequent in-depth study." (PMID 38835789, 2024). "Hence, this greatly confirms the critical role of RELA in PCa development and metastasis, and is most likely a novel therapeutic target." (PMID 38835789, 2024). "In addition, cellular experiments and immunohistochemistry confirmed that overexpression of RELA significantly inhibited the proliferation and migration of PCa cells, and RELA was significantly low-expression in bone metastasis." (PMID 38835789, 2024).
pheochromocytoma (1 paper, 2023). "These include the reported upregulation by hsa-miR-324-3p of RELA expression in the pheochromocytoma PC-12 cell line that leads to an increased production of the pro-apoptotic caspase-3 protein." (PMID 36902315, 2023).
pneumococcal pneumonia (1 paper, 2020). A febrile disease caused by STREPTOCOCCUS PNEUMONIAE. "During pneumococcal pneumonia, NF-κB RelA in macrophages is crucial for early cytokine expression, neutrophil recruitment, and lung defense." (PMID 32300347, 2020).
pneumonitis (1 paper, 2023). An inflammatory process affecting the lung parenchyma. "In conclusion, the evaluation of EV protein expression identified RELA as a potential predictive marker of symptomatic pneumonitis in patients treated with durvalumab after CCRT." (PMID 37614219, 2023). "We found that RELA, which represents NF‐κB signaling, was elevated in patients who developed symptomatic pneumonitis after durvalumab treatment." (PMID 37614219, 2023). "Furthermore, protein–protein interaction analysis showed that RELA was interrelated with CHUK, ROCK1, and ROCK2, and we chose RELA as a candidate EV protein to predict symptomatic pneumonitis." (PMID 37614219, 2023).
postmenopausal osteoporosis (1 paper, 2022). Metabolic disorder associated with fractures of the femoral neck, vertebrae, and distal forearm. "The NF-κB1, RELA, and NLRC5 genetic variations affect the therapeutic response of alendronate treatment for postmenopausal osteoporosis." (PMID 35368772, 2022).
preeclampsia (1 paper, 2022). Preeclampsia is a hypertensive disorder of pregnancy that is characterized by new-onset hypertension with proteinuria presenting after 20 weeks of gestation, and depending on mild or severe forms may initially present with severe headache, visual disturbances, and hyperreflexia. "The binding energy between curcumin and TPBG-4cnc, OPRK1-4djh, and RELA-3qxy was less than −7.0 kcal/mol, which further suggested the effectiveness of curcumin for the treatment of preeclampsia." (PMID 35880174, 2022).
primary effusion lymphoma (1 paper, 2024). A large B-cell lymphoma located in the body cavities, characterized by pleural, peritoneal, and pericardial fluid lymphomatous effusions and that is always associated with human herpes virus-8 (HHV-8). "In the KSHV-positive primary effusion lymphoma (PEL) cell line BCBL-1, depletion of CAD by CRISPR/Cas9 near-abolished cell proliferation in vitro, which can be partially rescued by the expression of RelA-DD." (PMID 38365882, 2024).
progeroid syndrome (1 paper, 2020). A group of rare genetic disorders which mimic physiological aging, making affected individuals appear to be older than they are. "Genetic depletion of RelA/p65 in aged mouse skin and a mouse model of human progeroid syndrome, reversed gene expression signature of aging and aging phenotypes." (PMID 32201398, 2020).
Prostatic intraepithelial neoplasia (1 paper, 2005). "Prostatic intraepithelial neoplasia samples expressed weak to strong cytoplasmic levels of NF-κB subunits and only one core (one out of 23) demonstrated RelA nuclear staining." (PMID 16205698, 2005).
pterygium (1 paper, 2018). A wedge-shaped fibrovascular lesion arising from the bulbar conjunctiva and extending to the cornea. "Mean expression levels of NFκB1, NFκB2 and RELA genes were 2.4±0.3, 1.9± 0.5, and 1.8±0.4 times higher in patients with pterygium in comparison with controls, respectively." (PMID 31565648, 2018). "This study has indicated a significant association between expressions of inflammatory-related NFκB1, NFκB2 and RELA genes, and pterygium." (PMID 31565648, 2018). "We examined the changes in expression of 3 inflammatory related NFκB1, NFκB2, and RELA genes in patients with pterygium." (PMID 31565648, 2018). "In this study, we evaluated the probable associations between the mean expression levels of NFκB1, NFκB2 and RELA genes in the pterygium." (PMID 31565648, 2018). "Moreover, a significant correlation was observed between the expression levels of NFκB2 and RELA genes, suggesting a possible NFκB2- RELA heterodimer formation in patients with pterygium." (PMID 31565648, 2018). "We also found a positive correlation between NFκB2 and RELA genes in the pterygium patients." (PMID 31565648, 2018). "Hence, we evaluated the expression levels of three main genes of NFκB family including NFκB1, NFκB2 and RELA in patients with pterygium and controls." (PMID 31565648, 2018).
reovirus infection (1 paper, 2010). "To determine whether cleavage-induced Bid activation is dependent on NF-κB, we examined Bid cleavage in cells lacking p65/RelA, an NF-κB subunit required for apoptosis induction following reovirus infection." (PMID 20617182, 2010).
Salmonella Infections (1 paper, 2022). Infections with bacteria of the genus SALMONELLA. "Other genes known to be associated with Salmonella infection were also upregulated, including a variety of chemokines, RELA, ARPC4 and MAPK3." (PMID 35711662, 2022).
sarcoidosis (1 paper, 2025). Sarcoidosis is a multisystemic disorder of unknown cause characterized by the formation of immune granulomas in involved organs. "Additionally, the miRNet tool showed three transcription factors (PPARG, NFKB1, and RELA) exhibited the highest levels of interaction with the common DEGs shared between sarcoidosis and LC." (PMID 40797277, 2025).
soft-tissue tumor (1 paper, 2022). "Lastly, SRF::STAT6 fusion was reported in a case of deep soft-tissue tumor of the arm in a 15-year-old boy, expressing a full smooth-muscle phenotype and overlapping features with the SRF::RELA myofibromas." (PMID 36421692, 2022).
synovial sarcoma (1 paper, 2009). "In synovial sarcoma cells, we findthat nuclear levels of the RelA subunit of NF-κB increase during MS-275 treatment, butdecrease in the presence of 17-AAG as a single agent or in combination withMS-275." (PMID 19325926, 2009).